PPARG (peroxisome proliferator activated receptor gamma)
Diseases named in the same sentence as PPARG in open-access papers (continued):
Sharing a sentence is not in itself a finding about the gene and the disease.
Alzheimer disease (continued). "There are increasing evidences demonstrating that pharmacological activation of PPARγ confers to neuroprotection in experimental models of ischemic injury, Alzheimer's disease, and autoimmune encephalomyelitis." (PMID 23762140, 2013). "Protective effects have been seen with PPARγ agonists in murine models of Alzheimer's disease, Parkinson's disease (PD), amyotrophic lateral sclerosis, Huntington's disease and multiple sclerosis." (PMID 22417924, 2012). "Peroxisome proliferator-activated receptor γ (PPARγ) agonists have been shown to provide neuroprotection in a number of neurodegenerative diseases including Parkinson's disease and Alzheimer's disease." (PMID 22417924, 2012). "Peroxisome proliferator-activated receptor-γ (PPARγ) has been reported to be involved in the etiology of pathological features of Alzheimer's disease (AD)." (PMID 22163051, 2011). "In contrast, PPARγ expression was shown to be elevated in brains of patients with Alzheimer's disease, in bronchial epithelium and airway smooth muscle cells of asthmatic patients, and in T cells isolated from patients with sepsis." (PMID 17386086, 2007). "Studies with PPARγ drugs in animal models of neurological conditions have led to clinical testing of these drugs in Alzheimer's disease (AD) and multiple sclerosis (MS)." (PMID 17207275, 2007). "Notably, the role of PPARG in mitochondrial regulation and its implications in Alzheimer’s Disease (AD) cannot be overlooked." (PMID 39757625, 2025). "Consistently, carriers of rs1151999-G, together with three other PPARG SNPs, were strongly protected against Alzheimer’s disease when they did not carry the ε4 allele of apolipoprotein E (APOE), indicating a gene–gene interaction." (PMID 37047733, 2023). "In a murine model of Alzheimer's disease, PPARγ was found to play a crucial role in the attenuation of inflammation, which may be associated with modulation of M1/M2 polarization." (PMID 37401041, 2023). "Moreover, berberine and pioglitazone have similar binding affinity to peroxisome proliferator-activated receptor gamma (PPARγ) protein, have an overlapping effect on Alzheimer’s disease." (PMID 35668943, 2022). "Therefore, the results obtained both in vitro and in vivo confirm the important role of PPARγ in mediating the neuroprotective actions of CBD in experimental models of Alzheimer’s disease." (PMID 33171772, 2020). "Further, PPARγ agonists improved memory in some humans with early Alzheimer’s disease." (PMID 31396113, 2019). "In addition, the effect of PPARγ in the well-known neuron disease Alzheimer’s disease (AD) has also been widely investigated." (PMID 31336903, 2019). "This constitutes a potential advantage of PFV technology in scenarios requiring expression localized to the hippocampus, such as in the recent correction of an Alzheimer’s disease model by LV-mediated peroxisome proliferator-activated receptor gamma (PPARγ) coactivator 1α gene transfer." (PMID 30081233, 2018). "Also identified was a novel PPARγ modulator, idebenone, which was first developed as a CoQ10 analog for potential use in Alzheimer's disease." (PMID 30171034, 2018). "PPARγ levels were found to decrease in the brains of Alzheimer’s disease patients." (PMID 29734791, 2018). "Moreover, pioglitazone is the only approved PPARγ agonist with significant ability to cross the blood-brain barrier and has demonstrated neuroprotective benefits in models of Alzheimer’s disease, Parkinson’s disease, epilepsy, and stroke." (PMID 29182629, 2017). "Activation of PPARγ signaling has a protective role by reducing neuroinflammation, a finding which may present a novel therapeutic approach for diseases, including Alzheimer’s disease, Parkinson’s disease, stroke, schizophrenia, and autism." (PMID 27716270, 2016).
Alzheimer disease (continued). "In this review, we explore the evidence for potential beneficial effects of PPARγ agonists in a number of neurological disorders, including Parkinson’s disease, Alzheimer’s disease, Amyotrophic lateral sclerosis and Huntington’s disease, ischaemia, autoimmune encephalomyelitis and neuropathic pain." (PMID 27352979, 2016). "There is evidence that PPARγ agonists could improve the neurological outcomes in the variable central nervous system diseases, such as Alzheimer’s disease, multiple sclerosis, Parkinson’s disease, and acute cerebral ischemia." (PMID 26659605, 2015). "One of the important roles of PPARγ in the control of inflammation may be related with regulation of M1/M2 phenotype as demonstrated in a post-incisional pain study and Alzheimer’s disease model." (PMID 25889216, 2015). "Accumulating evidence suggests PPARγ agonists may be useful for treating or delaying the onset of Alzheimer’s disease (AD), possibly via actions on mitochondria, and that dose strengths lower than those clinically used for T2DM may be efficacious." (PMID 25671601, 2015). "PPARγ activation is another approach that can robustly induce the polarization of M2 microglia and may be a promising therapy for Alzheimer’s disease." (PMID 24889886, 2014). "The potential pathways of the PPARγ agonist in Alzheimer’s disease are fairly well known." (PMID 25356910, 2014). "In Alzheimer's disease, which is characterized by chronic neuroinflammation, PPARγ activation attenuates neuroinflammation and augments expression of M2 macrophage markers, indicating that peripheral administration of PPAR agonists can influence an active and chronic inflammatory milieu in the CNS." (PMID 24215544, 2013). "It would, however, be interesting to further explore if treatment with GW9662 and subsequently PPARγ antagonism has global neurotoxicity as suggested by studies in other neurodegenerative diseases including Huntington's disease and Alzheimer's disease." (PMID 22417924, 2012). "Interestingly, earlier studies have demonstrated that PPARγ is a potent regulator of inflammation and in vivo treatment with PPARγ agonists reduces clinical symptoms of MS, Alzheimer's disease, spinal cord injury, and stroke in animal models." (PMID 23185633, 2012). "The same study highlighted PPARγ as an important mediator of gut–brain communication and suggested it could serve as a future therapeutic target for probiotic or synbiotic approaches in managing complex chronic diseases such as Alzheimer’s disease." (PMID 41149774, 2025). "Given the anti-inflammatory effects of ABA in neuroinflammation and Alzheimer’s disease in combination with its capacity to activate PPARγ, we hypothesized that ABA could improve remyelination through modulation of macrophage phenotype and neuroinflammation in experimental models of MS." (PMID 39742273, 2024). "In addition, this study suggested that CBD, at least in part, through interaction with PPARγ, could be a therapeutic potential for the treatment of Alzheimer’s disease." (PMID 33171772, 2020). "Ultimately, the study of PPARγ is expected to provide a new therapeutic approach for the treatment of ischemic cerebrovascular diseases, and it is important for the prevention of neurodegenerative diseases such as Parkinson's disease, Alzheimer's disease, and Huntington's disease." (PMID 33281727, 2020). "The potential of lignanamides in Alzheimer’s disease treatment was tested by verifying its effect on BACE 1, PPARγ, and PGC-1α expression in amyloid β precursor protein (APP)-producing N2a cells." (PMID 40364401, 2025). "With the analysis of the increased expression of Peroxisome Proliferator-Activated Receptor Gamma (PPARγ) evidenced in snRNA-seq data, an increased amount was observed in the fraction of PPARγ+P2RY12+ cells in Alzheimer’s disease patients." (PMID 39861194, 2025).
Alzheimer disease (continued). "New-generation TZDs with decreased affinity for PPARγ maintain the therapeutic benefit and have been considered in clinical trials for MASH and Alzheimer’s disease." (PMID 40249800, 2025). "Moreover, CBD as PPARγ agonist may be helpful in treatment of Alzheimer’s disease." (PMID 37111244, 2023). "Their potential for the treatment of Alzheimer’s disease is based on the ability of the plant extract to activate PPAR-α (peroxisome proliferator-activated receptor alpha) and PPAR-γ (peroxisome proliferator-activated receptor gamma) selectively." (PMID 37241796, 2023). "On the other hand, the therapeutic effects of BCP over Alzheimer’s disease rely mainly on CB2R activation, and to a lesser extent, on PPARγ activation." (PMID 33498245, 2021). "Hence, these three bioactive lipids (resolvin E1, neuroprotectin D1 and hydroxy-linoleic acid) may be favourably considered as ideal drug candidates in therapeutic modulation of clinical conditions such as type 2 DM, Alzheimer’s disease and other instances where PPARγ is a key player." (PMID 28109294, 2017). "While it has been explored in clinical trials for anticancer therapies, this drug has not been applied to PPARG agonism in the context of Alzheimers Disease, representing a missed opportunity." (PMID 41256885, 2025). "In addition, in the common carp liver, the KEGG pathway analysis showed that Alzheimer’s disease was related to genes INSR, GAPDHS, BAX, DHCR24, PPARG, ENO1, and VEGFA." (PMID 35741857, 2022). "PPARγ activation is positively related to ameliorating experimental autoimmune encephalomyelitis (EAE) in mice and reducing amyloid deposition along with improving cognitive function in Alzheimer’s disease models." (PMID 25889216, 2015). "Furthermore, the group reported PPARγ-dependent effects of NPD1 in in vitro and 3x-Tg-AD mouse models of Alzheimer's disease." (PMID 26713087, 2015). "The peroxisome proliferator-activated receptor-gamma (PPAR-γ), a ligand-inducible transcription factor that forms part of the nuclear receptor superfamily, exhibits notable expression in microglial cells and plays a critical role in the pathogenesis of Alzheimer’s disease." (PMID 39596378, 2024).
colorectal cancer (130 papers, 2006 to 2026). A primary or metastatic malignant neoplasm that affects the colon or rectum. "Increased expression of PPARG high expression increased the malignancy-associated traits such as proliferation in colorectal cancer cell lines and increased sensitivity toward the chemotherapeutic agent 5-FU." (PMID 40149317, 2025). "Changes in PPARγ expression and activity can influence the development of colorectal cancer (CRC) by changing the way lipids are processed, causing inflammation, and impacting insulin sensitivity." (PMID 39148124, 2024). "In line with this, somatic PPARG mutations have been reported in ~8% of sporadic colorectal cancers." (PMID 33716977, 2021). "The functional single nucleotide polymorphisms in peroxisome proliferator-activated receptor gamma (PPARG) gene were predicted to be correlated with the susceptibility of colorectal cancer (CRC)." (PMID 29246001, 2017). "Other groups have also determined this involvement: exposure ofcultured human colorectal cancer cell lines to PPARγ agonistsinhibits growth, associated with G1 cell cycle arrest, and it increasesseveral markers of differentiation." (PMID 17389773, 2007). "Our findings about PPARγ and polyamine metabolism in mutated K-ras colorectal cancer seem to follow this direction." (PMID 16854216, 2006). "The mice developed multiple polyps in the colon, suggesting that PPARγ activation may provide a molecular link between a high-fat diet and an increased colorectal cancer risk." (PMID 37251321, 2023). "In addition, most studies support the anti-cancer effects of PPARγ; for instance, a 2019 study found that high expression of PPARγ was associated with a good prognosis in patients with colorectal cancer." (PMID 37251321, 2023). "A high expression of PPARγ is associated with a favorable prognosis in colorectal cancer patients." (PMID 33946986, 2021). "So far, six unique somatic PPARG mutations in colorectal cancers have been reported." (PMID 33716977, 2021). "Although the first evidence on the potential link between PPARγ and intestinal disease established a correlation between this receptor expression and an increase in colon tumorigenesis, recently, many researchers have re-examined the association between PPARγ and the risk of colorectal cancer (CRC)." (PMID 33498177, 2021). "In addition, a PPARG germline mutation found in a patient with colorectal cancer impairs the transactivation potential and impedes agonist positioning." (PMID 33266062, 2020). "Furthermore, PPARG expression is independently associated with prolonged survival in colorectal cancer, as demonstrated in two separate prospective cohorts, corroborating the findings of the present study in OS patients." (PMID 32039832, 2020). "Moreover, PPARG methylation deregulation has been described in the context of colorectal cancer, hepatitis B and liver inflammation and fibrosis associated with hepatitis B." (PMID 30642114, 2019). "There are many conjectures whether the pathways linked to autophagy and those activated by PPARγ are connected and related to cancer cell survival and colorectal cancer tumorigenesis." (PMID 28932171, 2017). "Conclusively, PPARγ is closely associated with the occurrence, development, proliferation, and prognosis of colorectal cancer and may become a novel molecular biomarker for clinical staging of colorectal cancer and a promising therapeutic target for colorectal cancer." (PMID 29483923, 2018). "Thus, it is possible that PPARG rs1801282 C>G polymorphism may be a protective factor for colorectal cancer through insulin-related mechanisms." (PMID 29246001, 2017). "In the same line, PPARG promoter methylation in colorectal carcinoma (CRC) is associated with poor prognosis." (PMID 27579030, 2016).
colorectal cancer (continued). "While the exact mechanism for thiselevated risk is still unknown, recent studies have been investigating whetherthe marked reduction in levels of the nuclear receptor PPARγ in colons of UC patients may play a role intheir increased susceptibility to developing colorectal cancer." (PMID 19390648, 2009). "These integrated findings establish that PGC1α exerts its tumor-suppressive effects in colorectal cancer through PPARγ-dependent modulation of WNT/β-catenin signaling." (PMID 40603870, 2025). "Hydroxysafflor Yellow A (HSYA), present at 8.49% in BESD and 8.07% in BF1SD, exhibits remarkable antiproliferative properties by inhibiting the proliferation, migration, and invasion of colorectal cancer cells through the PPARγ/PTEN/Akt signaling pathway." (PMID 40942095, 2025). "Globally, colorectal cancer ranks as the third most prevalent malignancy and is responsible for approximately 10% of all cancer mortalities, and PPARG is significantly expressed in 70% of the sporadic CRC." (PMID 40500799, 2025). "PPARG expression as a prognostic effect depends on metastasis localization in advanced colorectal cancer patients." (PMID 40149317, 2025). "Promoter hypermethylation of the PPARG gene by ubiquitin-like, containing PHD and RING finger domains, 1 (UHRF1) are associated with poor prognosis in colorectal cancer." (PMID 39195246, 2024). "Peroxisome proliferator-activated receptor gamma (PPARγ) plays a crucial role in controlling lipid metabolism and energy balance, which are important biological processes involved in the advancement of colorectal cancer (CRC)." (PMID 39148124, 2024). "The ALOX15-derived metabolite 13-(S)-HODE has been shown to augment the MAP kinase signaling pathway and diminishes PPARγ in colorectal cancer cells." (PMID 38612771, 2024). "A study by Wang and colleagues reported that the stimulation of PPARγ induces cell death through the downregulation of survivin expression and the increase in caspase 3 activity in colorectal cancer cells." (PMID 38611871, 2024). "The results demonstrate that increased expression of ZDHHC6 can stimulate the production of fatty acids in living organisms by activating PPARγ, hence promoting the advancement of colorectal cancer." (PMID 39148124, 2024). "Subsequently, we assessed the predictive significance of ZDHHC6 and PPARγ in these datasets of colorectal cancer tissue microarrays (TMA)." (PMID 39148124, 2024). "In our in vitro experiments, we showed that activation of PPARG by pioglitazone and rosiglitazone leads to a dose-dependent increase in proliferation rate in the colorectal cancer cell lines HT29 and SW403." (PMID 38378472, 2024). "PPARγ agonists have been shown to increase PD-L1 protein expression in human gastrointestinal and colorectal cancer cell lines." (PMID 38611871, 2024). "Recent research have shown that the process of phosphorylation of AKT stimulates the production of PPARγ, which in turn enhances the synthesis of lipids and the development of tumors in colorectal cancer (CRC)." (PMID 39148124, 2024). "In conclusion, through communication with MDC1, ID3 and PPARγ formed a positive feedback loop to promote the repair of DNA damage, thus affecting the radiosensitivity of colorectal cancer cells." (PMID 37170184, 2023). "In colorectal cancer, HIF1A, MMP9, and PTGS2 had the highest mutation frequency at 5.8%, 7.7%, and 5.8%, respectively, while in melanoma, PPARG and TGFB1 had the highest mutation frequency at 4.7% and 1.9%, respectively." (PMID 37033970, 2023). "The cooperative effects of RXR and PPARγ agonists have also been observed in colon and colorectal cancer cells." (PMID 37645246, 2023). "ID3 and PPARγ influence the radiosensitivity of colorectal cancer cells by interacting with MDC1 to form a positive feedback loop that promotes DNA damage repair." (PMID 37170184, 2023).